IL7 (interleukin 7)
Diseases named in the same sentence as IL7 in open-access papers (continued):
Sharing a sentence is not in itself a finding about the gene and the disease.
lymphopenia (continued). "Employing the protocol often results in lymphopenia that is associated with elevated serum levels of the homeostatic cytokines IL-7 and IL-15, which expands the autoreactive CD8+ T-cell population." (PMID 22013505, 2011). "CD8+ lymphopenia is also associated with raised circulating IL-7 levels but this correlation is less strong." (PMID 15642146, 2005). "Studies regarding the use of interleukin 7 (IL-7) have also demonstrated that supplementation may be able to reverse sepsis-associated lymphopenia." (PMID 40555121, 2025). "The present study confirms and extends findings from our earlier investigation demonstrating that administration of a glycosylated recombinant human IL-7 (CYT107) can effectively reverse the profound sepsis-induced lymphopenia that is a defining pathophysiologic hallmark of sepsis." (PMID 36906875, 2023). "On the other hand, the decreased IL-7 levels may explain the associated lymphopenia in the most severe cases as a result of exhaustion, as it is required for T-helper 17 development." (PMID 36499671, 2022). "Moreover, while IL-7 deficiency results in lymphopenia, overexpression of IL-7 can cause neoplasia in experimental models." (PMID 34206780, 2021). "For instance, HIV-1-induced lymphopenia is associated with increased levels of interleukin 7 (IL7)." (PMID 30254620, 2018). "Having shown that lymphopenia-associated IL-7 overabundance promotes IEC hyperplasia, we asked next whether IL-7 consumption by T cells is sufficient to normalize IEC homeostasis in Rag− mice." (PMID 22384106, 2012). "Due the broad impact of IL-7 on intestinal physiology shown here, it is tempting to speculate that the lymphopenia-associated overabundance of IL-7 promotes intestinal alterations frequently observed in lymphopenic patients." (PMID 22384106, 2012). "Thus, lymphopenia-associated IEC hyperplasia is associated with the accumulation of IL-7+ IEC in the colon." (PMID 22384106, 2012). "IL-7 is critically required for lymphocyte development and homeostasis, as first appreciated from the severe lymphopenia observed in IL-7 knockout and IL-7R knockout mice, and later on in comparable immune deficiencies in humans who lack either IL-7 or components of its receptor." (PMID 22768283, 2012). "In addition, IL-7 can serve as a costimulatory factor during T cell activation, a role that is particularly important in conditions associated with lymphopenia when IL-7 triggers hoemostatic proliferation." (PMID 22194871, 2011). "Thus, we speculate that the deficiency in the expression of CD127 might occur in severely ill patients, which culminates in the deficiency of cell proliferation induced by IL-7 and consequent lymphopenia." (PMID 33193331, 2020). "However, supporting its auspicious character, we also demonstrated that the early postoperative rise in IL-7 is associated with favorable outcomes, such as lower incidence of surgical-site infections, milder surgery-induced lymphopenia, and beneficial interferon-γ dynamics." (PMID 31185636, 2019). "Moreover, lymphopenia is associated with increased circulating levels of IL-7." (PMID 23551939, 2013). "CD127 can be downregulated by its ligand, the IL-7 cytokine, and circulating IL-7 concentration is known to increase in situations of lymphopenia, raising the possibility that chronic IL-7 stimulation in ICL may drive CD127 downregulation and cause a desensitization of IL-7 responses." (PMID 23383227, 2013). "We therefore asked next, whether lymphopenia-associated IEC hyperplasia is IL-7-dependent." (PMID 22384106, 2012). "Thus lymphopenia in humans should be associated with reciprocal increases in IL-7 levels." (PMID 21711552, 2011). "To investigate whether such an IL-7 deficiency could account for the prolonged lymphopenia observed in RA following therapeutic lymphodepletion, we compared RA patients and patients with solid cancers treated with high-dose chemotherapy and autologous progenitor cell rescue." (PMID 15642146, 2005).
lymphopenia (continued). "A recent double-blind, randomized, placebo-controlled trial investigated the intravenous administration of CYT107, a recombinant human interleukin-7 (IL-7), in patients with septic shock and severe lymphopenia." (PMID 41268545, 2025). "Some trials have attempted to reverse lymphopenia and immune paralysis in patients with sepsis using antibodies against interleukin-7 (IL-7) and programmed cell death protein (PD)-1, as well as other agents, with mixed results." (PMID 39967662, 2025). "In a mouse model of radiation-induced lymphopenia, interleukin-7 administration restored CD8-positive tumor-infiltrating lymphocytes." (PMID 41225450, 2025). "Third, exploring synergy with immunoadjuvants like interleukin-7 to reverse sepsis-induced lymphopenia." (PMID 40992080, 2025). "IL-7 has been demonstrated to reverse sepsis-induced lymphopenia and to augment T-cell proliferation and activation." (PMID 40153575, 2025). "Collectively, these data suggest a mechanism of prolonged, lymphopenia-driven increase of systemic IL-7 and IL-15 concentrations after acute SARS-CoV-2 infection, which sustains increased IL-2R and decreased IL-7R expression." (PMID 41310351, 2025). "Other means of mitigating lymphopenia involve directly boosting lymphocyte counts via lymphocyte re-infusion, recombinant IL-7, and transient sequestration of lymphocytes using fingolimod." (PMID 38481255, 2024). "TJ107, a long-acting recombinant IL-7, is currently being evaluated in a phase II clinical trial for its effectiveness and safety in treating lymphopenia in glioblastoma patients post-CCRT (NCT04600817)." (PMID 38779093, 2024). "Studies have shown that acute inflammation can inhibit osteoblastic bone formation, leading to T and B lymphopenia due to decreased production of interleukin-7 (IL-7)." (PMID 38999948, 2024). "Remarkably, previous studies have shown that IL-7 administration can reverse sepsis-induced lymphopenia by inhibiting apoptosis and improving the proliferation of T lymphocytes, which was recently demonstrated in a clinical trial." (PMID 38909272, 2024). "In line with this concept, evidence from pre-clinical animal studies indicates that prevention of lymphopenia, for example by IL-7 administration, improves the long-term outcome of sepsis." (PMID 38984201, 2024). "Interleukin‐7 (IL‐7), which is a common gamma‐chain cytokine that plays critical roles in maintaining lymphocyte homeostasis, has been suggested to reverse lymphopenia and improve clinical outcomes of cancer patients." (PMID 36583472, 2023). "An increased circulating IL-7 level has been reported in HIV-1 infection, associating CD4+ T lymphopenia, and an increased IL-7 production was due to a homeostatic response to T cell depletion." (PMID 37298575, 2023). "Accordingly, “virtual memory” T cells are generated in peripheral tissues by IL-15 signaling, whereas “homeostatic memory” T cells are produced via lymphopenia-induced proliferation in peripheral organs in an IL-7- and IL-15-dependent manner." (PMID 37887277, 2023). "Homeostatic cytokines such as IL-7 are systemically elevated in the setting of lymphopenia, yet we showed that tissue levels of IL-7 were distinct." (PMID 37856221, 2023). "Altogether, these studies suggest that inflammation-induced lymphopenia is at least partly controlled by reduced IL-7 production in bone marrow MSCs." (PMID 36717247, 2023). "Interleukin‐7 (IL‐7) agonists have the potential to counteract the lymphopenia frequently seen in GB patients, revitalizing immune function through the stimulation of T cell growth and proliferation." (PMID 38069593, 2023). "In particular, novel therapies such as IL-7 immunotherapy have been previously explored in animal models to enhance lymphocyte recovery after treatment-induced lymphopenia." (PMID 36810555, 2023).
lymphopenia (continued). "This clinical potential is supported by many animal studies evaluating effects of recombinant forms of IL-7 in models of lymphopenia, infectious disease and sepsis, and cancer." (PMID 37874823, 2023). "Including cytokine‐based treatments, such as IL‐7 agonists, in GB regimens not only addresses therapy‐induced lymphopenia but also enhances the overall effectiveness of immunotherapeutic approaches." (PMID 38069593, 2023). "In this manner, we sought to gain further insight into the safety and efficacy of IL-7 as a potential immune adjuvant in the therapy of sepsis-induced lymphopenia." (PMID 36906875, 2023). "A previous phase II study showed that CYT107, a glycosylated recombinant human IL-7, administered intramuscularly reversed sepsis-induced lymphopenia and improved lymphocyte function." (PMID 36906875, 2023). "It has been reported that IL-7 therapy can increase functional T cells and reverse profound lymphopenia." (PMID 37373104, 2023). "It is possible that IL-7 can also be beneficial in overcoming glucocorticoid or chemotherapy-induced lymphopenia, resulting in refractory MAS." (PMID 36189240, 2022). "Its increase produces a diminishing of the circulating IL-7 level, which interacts with the lymphocyte’s membrane receptor, determining lymphopenia." (PMID 35907923, 2022). "In a recent study, it is proved that exogenous IL-7 can be beneficial in overcoming radiation-induced lymphopenia." (PMID 36189240, 2022). "The administration of anti-inflammatory effectors, such as IL-7, was shown to reverse lymphopenia and increase CD4+/CD8+ T-cell proliferation in septic shock." (PMID 36680144, 2022). "As a feedback response to lymphopenia, serum IL-7 concentration was also negatively related to the number of T cells, CD4+ and CD8+ cells, highlighting the link between lymphopenia and higher IL-7 levels in SARS-CoV-2 infection." (PMID 35958594, 2022). "Others are evaluating drugs like recombinant IL-7 or anti-PD-L1 therapy in septic patients with lymphopenia." (PMID 34684188, 2021). "IL-7, a cytokine produced by thymic epithelial cells in response to lymphopenia, was measured as an indicator of functioning thymic stroma." (PMID 33651234, 2021). "Low levels of IL-7 are detectable in human serum, and increased IL-7 production is thought to be a compensatory effect of lymphopenia in numerous disease states." (PMID 35185860, 2021). "In this work, we analyzed the in vitro effect of IL-7 on MAIT cells of only mildly affected patients as we had limited samples from the severely affected patients which presented with severe lymphopenia and thus had very few MAIT cells still present." (PMID 34238985, 2021). "Interleukin-7 (IL-7) is a cytokine that reverses sepsis-induced lymphopenia, prevents apoptosis, and induces T cell proliferation." (PMID 33803628, 2021). "Homeostatic proliferation (HP) is a physiological process that reconstitutes the T cell pool after lymphopenia involving Interleukin-7 and 15 (IL-7 and IL-15), which are the key cytokines regulating the process." (PMID 33809452, 2021). "The revealed decrease in Treg proliferation under IL-7 and IL-15 exposure can lead to a delay in Treg pool reconstitution in patients with rheumatoid arthritis in the case of lymphopenia." (PMID 33809452, 2021). "IL-7 is known to be secreted continuously by stromal cells and under normal circumstances therefore ensuring survival of T lymphocytes, but in cases of lymphopenia elevated IL-7 levels are observed." (PMID 34208325, 2021). "Nevertheless, for example, IL-7- and IL-15-driven T cell proliferation induced by lymphopenia can promote the numerical recovery of T cells." (PMID 34305933, 2021). "In patients with septic shock and lymphopenia, IL-7 has been shown to reverse sepsis-induced lymphopenia." (PMID 32582139, 2020).
lymphopenia (continued). "Instead, repopulation of the peripheral T cell population is predominantly driven by lymphopenia-induced proliferation, mediated by the increased availability of γc cytokines, such as IL-7 and IL-15." (PMID 33013907, 2020). "Recombinant human IL-7 (rhIL-7) was shown to improve the immune function of patients with lymphopenia by promoting peripheral T cell expansion and suppressing the immunosuppressive network." (PMID 31938023, 2020). "IL-7 signaling contributes to T cell proliferation in response to lymphopenia and can mask TCR mediated proliferation." (PMID 32047502, 2020). "A clinical trial of IL-7 in patients with sepsis showed that IL-7 was well tolerated, reversed sepsis-induced lymphopenia, and increased CD4+ and CD8+ T cells by 2- to 3-fold." (PMID 32687484, 2020). "T cell numbers were significantly higher in PTPN22 KO than in WT mice when IL-7 signaling was blocked indicating that the availability of IL-7 can mask dysregulated self-peptide MHC/TCR mediated proliferation during lymphopenia." (PMID 32047502, 2020). "Since the protective role of IL-7 signal during the treatment-related lymphopenia, the serum level of IL-7 was determined by ELISA." (PMID 31138762, 2019). "The first phase II clinical trial of IL-7 indicated the capacity of the IL-7 treatment in restoring T-cell count in septic shock patients with severe lymphopenia." (PMID 30995946, 2019). "As a critical cytokine for T-cell development and homeostasis of mature T cells, IL-7 accumulates during lymphopenia, leading to increased T-cell proliferation." (PMID 31138762, 2019). "It has been related to some favorable outcomes as well—IL-7 overexpression correlated with better survival in patients with head and neck cancers, improved wound healing, milder surgery-induced lymphopenia, and lower incidence of surgical-site infections." (PMID 31185636, 2019). "During lymphopenia, an IL-7-rich environment provides a milieu for the proliferative expansion of T cells." (PMID 31024566, 2019). "IL-2, IL-7 and IL-15 are three cytokines playing a role in the development, proliferation and survival of T cells that have been evaluated to restore lymphopenia." (PMID 30922400, 2019). "In mouse models of chemotherapy-induced lymphopenia, IL-7 accelerates CD4+ and CD8+ T cell repopulation in spleen and lymph nodes." (PMID 30922400, 2019). "Adjunctive corticosteroids reduce mortality in adults with severe pneumonia and sepsis, and adjunctive recombinant IL-7 is well tolerated in sepsis and results in more rapid and sustained recovery of sepsis-induced lymphopenia." (PMID 31276515, 2019). "An immune reconstitution is observed in murine and baboon allogeneic HSCT models treated with IL-7 and has recently been evaluated to counteract IFNα-induced lymphopenia and treat SIV infected monkeys." (PMID 30922400, 2019). "Findings suggest that IL-7 immunotherapy has a net positive effect with regard to increasing T-cell numbers and survival and in SIV-infected Rhesus macaques, IL-7 therapy aided to overcome IFN-α treatment-induced lymphopenia." (PMID 29261677, 2017). "Recent reports have suggested that lymphopenia-induced homeostatic proliferation favors survival and expansion of Ag-stimulated T-cells due to the ability of endogenous IL-7 to rescue TCR-triggered T-cells from a proapoptotic state." (PMID 27974697, 2017). "In AIDS patients with deep lymphopenia, overexpression of IL-7 by dendritic-like cells or macrophages was evidenced in LNs." (PMID 28579989, 2017). "Upon IL-7 therapy, transient lymphopenia was observed in HIV-infected patients as well as in healthy macaques." (PMID 28579989, 2017). "When the peripheral T cell number is reduced (lymphopenia), the serum concentration of IL-7 rises to supraphysiological levels." (PMID 26983628, 2016). "We next assessed the stimulatory effect of IL-7 and IL-15 on Te cells, thus mimicking the situation of our study of the in vivo effect of IL-15 signaling on transferred Te cells in lymphopenia." (PMID 27158441, 2016).
lymphopenia (continued). "It has been shown that lymphopenia induces IL-7 secretion and the subsequent proliferation of T cells, antagonizing immune suppression; however, more studies are needed to clarify the detailed role of IL-7 in the induction of the antitumor effects." (PMID 27445423, 2016). "Homeostatic expansion, a process linked to CD5 expression level, is assumed to be driven by ‘self’ antigen when resources (e.g. IL-7) are abundant, as is the case in lymphopenia." (PMID 27881740, 2016). "An increase in the incidence of diabetes was reported only when lymphopenia was induced with cyclophosphamide or by exogenous administration of IL-7." (PMID 26983628, 2016). "Recombinant human IL-7 (rhIL-7) is an ideal solution for the immune reconstitution of lymphopenia patients by promoting peripheral T cell expansion." (PMID 25955647, 2015). "The induction of lymphopenia is well known to enhance lymphocyte responses to homeostatic cytokines, such as IL-15 and IL-7; however, the mechanism responsible for enhanced IL-15 responses has been unclear." (PMID 25756182, 2015). "A study proposed that the provision of exogenous or lymphopenia-induced endogenous IL-7 promotes the expansion of self-reactive clones, even in the presence of Treg cells, thereby explaining the relevance of IL-7 in the development of diabetes." (PMID 26636339, 2015). "In the setting of lymphopenia, the number of IL-7 receptor-bearing lymphocytes is decreased resulting in elevated plasma levels of IL-7, likely due to decreased consumption, a finding that emphasizes the role of IL-7 as a key regulator of T cell homeostasis." (PMID 26177551, 2015). "Lymphopenia-induced rapid proliferation occurs independently of IL-7 cytokine signals, but is thought to rely instead upon the TCR signal strength to available ligands within the lymphopenic host." (PMID 25781948, 2015). "IL-7 in vitro and lymphopenia in vivo differentially regulated expression of t-STATs in CD4 and CD8 T cells as well as their responses to Type-I IFN." (PMID 24603698, 2014). "Increased levels of IL-7 during lymphopenia are thought to be mainly the consequence of a decreased receptor-mediated clearance of IL-7 as the availability of receptors diminishes." (PMID 24853554, 2014). "In the present manuscript, we show that IL-7 in vitro or lymphopenia in vivo can upregulate the total levels of STAT1, -2 and -3, rendering CD4 T cells more sensitive to IFN-α." (PMID 24603698, 2014). "Lymphopenia can be promoted by IL-21-induced T cell death through inhibition of IL-7-mediated T cell survival in NOD mice." (PMID 24586733, 2014). "During HIV infection, production of some of these cytokines, such as IL-2 and IL-15, is downregulated, while IL-7 levels are increased as a consequence of lymphopenia." (PMID 26344343, 2013). "Increased IL-7 plasma levels in lymphopenic individuals is likely due to reduced consumption yet augmented production to counteract lymphopenia cannot be excluded." (PMID 22529911, 2012). "Several studies report that CD4+ lymphopenia driven by HIV-1 infection or bone marrow transplantation and idiopathic CD4+ T lymphopenia are often associated with increased serum levels of IL-7." (PMID 22474482, 2012). "All along the dimensions of lymphopenia, preclinical and clinical data have accumulated to demonstrate the ability of exogeneous IL-7 therapy to repair these multiple deficits." (PMID 22383042, 2012). "We therefore conclude that lymphopenia-related IL-7 overabundance is the major reason for IEC hyperplasia in Rag− mice and protection from DSS-induced colitis." (PMID 22384106, 2012). "Lymphopenia induced proliferation is driven by an increased availability of cytokines (notably IL-7) and access to self-pMHC due to eradication of competing host cells." (PMID 22879925, 2012).